LRTM2 (leucine rich repeat transmembrane protein 2)
Tractability: Antibody: UniProt predicts a signal peptide or a membrane-spanning region.
Gene: Protein-coding gene on chromosome 12 (1,820,267 to 1,836,753, forward strand). Ensembl gene ENSG00000166159.
Subcellular location: Membrane
Subcellular location (Human Protein Atlas): Cytosol
Gene Ontology:
Cellular component: membrane
Genetic constraint (gnomAD): Loss-of-function variants: 18 observed, 25.87 expected, observed/expected ratio (o/e) 0.7, 90% interval 0.48 to 1.03. The upper end of that interval is the gene's LOEUF score, 1.03, which puts it in group 4 of 6, group 1 being the genes least tolerant of losing a copy. Missense variants: 436 observed, 492.86 expected, observed/expected ratio (o/e) 0.88, 90% interval 0.82 to 0.96. Synonymous variants: 250 observed, 219.08 expected, observed/expected ratio (o/e) 1.14, 90% interval 1.03 to 1.27.
Homologues: Orthologues: chimpanzee LRTM2 (99% identical), dog LRTM2 (94% identical), macaque LRTM2 (94% identical), mouse Lrtm2 (92% identical), rat Lrtm2 (92% identical), rabbit LRTM2 (91% identical), guinea pig LRTM2 (90% identical), pig LRTM2 (88% identical), tropical clawed frog lrtm2 (70% identical), zebrafish lrtm2a (56% identical), zebrafish zgc:153913 (22% identical). Paralogues in human: SLIT3 (28% identical), LRFN2 (27% identical), SLIT2 (27% identical), SLIT1 (26% identical), LRFN4 (26% identical), LRFN1 (26% identical), LRFN5 (25% identical), LRRN2 (25% identical), LRFN3 (24% identical), SLITRK5 (23% identical), LRRN3 (23% identical), LRRN1 (22% identical), and 13 more.
Diseases named in the same sentence as LRTM2 in open-access papers:
LRTM2 is named in the same sentence as 3 diseases in open-access papers, as found by Europe PMC text mining. Sharing a sentence is not in itself a finding about the gene and the disease. The quoted sentences say what the papers report.
Nephroblastoma (1 paper, 2023). An embryonal neoplasm characterized by the presence of epithelial, mesenchymal, and blastema components. "We screened four highly expressed m6A-related genes (ADGRG2, CPD, CTHRC1, LRTM2) in nephroblastoma and constructed an effective diagnostic model based on these genes." (PMID 37938417, 2023).
neurological disorders (1 paper, 2024). "OMG, LRTM2, GRIK1, and CDH9 are predominantly expressed in the nervous system, participating in neuronal and synaptic functions, has a significant impact on the occurrence of various neurological disorders." (PMID 38979414, 2024).
tumor (1 paper, 2016). "An abridged list contains 23 hypermethylated genes and 4 hypomethylated genes (CACNA2D4;LRTM2, ESPNL, SECTM1, PCDH8) for AA tumor samples; whereas, 29 hypermethylated genes and 1 hypomethylated gene (BRSK2) are listed for the CA tumor samples." (PMID 27111221, 2016).